MTOR (mechanistic target of rapamycin kinase)
Diseases named in the same sentence as MTOR in open-access papers (continued):
Sharing a sentence is not in itself a finding about the gene and the disease.
cancer (continued). "Consequently, alterations in PI3K/Akt/mTOR pathway can disrupt cellular homeostasis, alter protein synthesis, and skin cell growth, promoting inflammation and cancer growth." (PMID 35163615, 2022). "Recent findings reveal diverse functions for lncRNA involved in the mTOR signaling regulation; thus, lncRNAs have emerged as therapeutic targets due to their ability to modulate multiple pathways in regulation of proteins or RNA molecules in human cancers." (PMID 36146655, 2022). "Emerging evidence demonstrated that the aberrant activation of PI3K/AKT/mTOR pathway could modulate epithelial-mesenchymal transition, autophagy, chemoresistance and metastasis in several human cancers." (PMID 36151545, 2022). "Since the aberrant activation of the PI3K/AKT/mTOR signaling pathway often happens in most of the human cancers, targeting this pathway may be a valuable strategy for the treatment of cancer." (PMID 35281608, 2022). "These therapies suggest that while inhibitors targeting the PI3K/AKT/mTOR pathways and its downstream proteins can produce antitumor effects, they may possibly be enhanced by combining them with various other cancer treatments." (PMID 35326708, 2022). "The effect of therapy based on 5-fluorouracil and cisplatin is known to be associated with changes in the expression profiles of the intracellular signaling cascade components (the AKT/mTOR signaling cascade and autophagy markers) and can predict the effect of the anti-cancer treatment." (PMID 35877414, 2022). "One of the possible mechanisms for resistance in ER+HER2-cancers might be due to the dysregulation of phosphoinositide 3 kinase (PI3K)/Akt/mammalian target of rapamycin (mTOR) signalling pathway." (PMID 35845921, 2022). "However, all other AKT pathway components, including PI3Ks, PDK1, AKT, and various isoforms of mTOR, are also the focus of drug development and molecularly targeted cancer therapies." (PMID 36429034, 2022). "Downregulation of PI3K/AKT leads to mTOR inactivation and induces autophagy in cancer cells." (PMID 35465266, 2022). "The abnormality of mTOR activation in cancer offers opportunities for targeted therapy." (PMID 35883111, 2022). "In cancer cells, interactions between MTOR and GPX4 can regulate autophagy-dependent ferroptosis by inhibiting CMA, and MTOR inhibitors may promote GPX4 degradation by activating the CMA pathway." (PMID 36093072, 2022). "Moreover, examining gene expression data of KRAS-mutant cancer cells revealed that NOP56 silencing significantly enriched the mTOR gene signature." (PMID 35039048, 2022). "In addition, the activation of PI3K/Akt/mechanistic target of rapamycin (mTOR) pathway has become a marker of the occurrence of many cancers, and in NSCLC, the PI3K/Akt/mTOR pathway is closely related to tumorigenesis and disease progression." (PMID 36339610, 2022). "Moreover, dysregulation of mTOR is allied with many human diseases, like cancer and neurological and metabolic diseases, with more focus now shown on mTOR’s role in the AD’s pathology." (PMID 36618946, 2022). "To date, several studies reported that various PI3K/Akt/mTOR inhibitors could overcome chemoresistance in many cancer cells such as BEZ235, CMG002, and PKI-402." (PMID 35783514, 2022). "Consistent with the inhibition of the PI3K/Akt/mTOR pathway by prodigiosin in cancer, it might be involved in the metabolic reprogramming of Th cells and CD8+ T cells." (PMID 36577970, 2022). "Genes co-expressed with G2E3 may be enriched in the E2F and PI3K/AKT/mTOR signaling pathways and other cancer-related signaling pathways." (PMID 36517818, 2022). "In addition, drugs known to target the PI3K/AKT/mTOR axis were reported to enhance radiation sensitivity in cancer cell lines and cancer models in pre-clinical studies." (PMID 35626685, 2022).
cancer (continued). "In contrast, mTOR inhibitor treatment increased factor 1 scores in cancer organoids." (PMID 35668108, 2022). "Notably, the PI3K pathway is crucial to OSCC’s growth, and several medications decrease the multiplication of cancer cells by blocking the PI3K/AKT/mTOR signaling pathway." (PMID 36703786, 2022). "Stable anaerobic conditions within the tumor microenvironment may also upregulate the mTOR signaling pathway, further ensuring cancer progression and survival." (PMID 35327484, 2022). "Moreover, resistance to VEGFR TKI treatment can lead to cellular changes resembling senescence-associated secretory phenotypes (SASPs), promoting recurrence of tumor growth and cancer progression regulated by mTOR signaling and IL6." (PMID 36138026, 2022). "Studies that have investigated the role of DEPTOR in cancer indicate that DEPTOR levels are generally low across several tumor types, and that rescue of DEPTOR is an effective anti-cancer therapy, warranting further study of this novel protein in mTOR-dependent processes." (PMID 36388131, 2022). "As a result, mTOR has become a crucial cancer therapeutic target." (PMID 36109789, 2022). "Most of these pathways repress the downstream signaling pathway mediated by protein kinase B (PKB, best known as AKT) and mammalian target of rapamycin (mTOR), thus deeply affecting the proliferation, migration and invasion of cancer cells and inducing apoptosis." (PMID 36110954, 2022). "Furthermore, mutations in the phosphatase and tensin homolog (PTEN) gene are the most well-known genetic abnormalities impacting mTOR signaling observed in human cancer." (PMID 36428613, 2022). "Further analyzing the subcellular distribution of mTOR and pmTOR has revealed elevated cytoplasmic mTOR/nuclear mTOR ratios (as well as cytoplasmic pmTOR/nuclear pmTOR ratios) in miR-99b-5p mimic vs. NS transfected cancer cells." (PMID 36077039, 2022). "This may be explained by pro-oncogenic role of CDCA5 during the cell cycle that impairs cancer apoptosis while promoting cell proliferation via the PI3K/AKT/mTOR signalling pathway, which was shown on our results at transcriptomic level." (PMID 36428736, 2022). "Emerging studies have indicated the unique functions of nuclear mTOR in cancers including PCa." (PMID 36077039, 2022). "Taken together, H-APBC nanocomplexes might be an effective mTOR inhibition-based cancer treatment strategy that could resist both hypoxia adaptation and TME acidosis in solid tumors." (PMID 35413842, 2022). "mTOR signaling pathway has been recently found on the crossroads of mechanoresponsive-induced signaling cascades to regulate cell growth, invasion, and metastasis in cancer cells." (PMID 35163745, 2022). "Since the abnormal mTOR signaling pathway is related to many diseases, especially cancer." (PMID 36085200, 2022). "In addition, it is also reported that pheophorbide-a based PDT reduces the phosphorylation of mTOR, which is involved in cancer cell proliferation." (PMID 35631388, 2022). "The phosphatidylinositol 3-kinase/protein kinase B/mammalian target of rapamycin (PI3K/AKT/mTOR) pathway is the most frequently and aberrantly activated pathway in many types of cancers and plays a key role in cancer cell growth, survival, angiogenesis, and metastasis." (PMID 36014303, 2022). "However, a study found that rapamycin, an mTOR inhibitor, significantly changed the miRNA expression profiles in cancer cells." (PMID 35883139, 2022). "Gene fusions are commonly found in the PI3K/AKT/mTOR axis in cancer development." (PMID 36539659, 2022). "To elucidate the anti-cancer activity in PDAC of HDACs/mTOR inhibitor 1 and pyrotinib, we firstly assessed whether it had synergy effect with pyrotinib." (PMID 36457011, 2022).
cancer (continued). "mTOR signaling is frequently upregulated in tumors with acquired cancer drug resistance as it, for example, protects from the cytotoxic DNA crosslinks induced by cisplatin by promoting DNA repair and counteracts the cytotoxic activity of PI3K-inhibitors (PI3Ki) by blocking apoptosis." (PMID 35681458, 2022). "Hence, inhibitors targeting PI3K, Akt, and mTOR have been evaluated in preclinical studies and clinical trials, and some inhibitors have been used clinically for cancer treatment." (PMID 36224343, 2022). "The Akt/mTOR signaling pathway is frequently overactivated in various types of cancer which may promote malignant cell survival and cancer progression." (PMID 35662690, 2022). "However, IFN-γ also activates AKT/mTOR pathway in cancer diseases, and induces PD-L1 expression, antagonizing its antitumor effect." (PMID 36313041, 2022). "mTOR is frequently activated in cancer and controls cell growth and metabolism." (PMID 36227107, 2022). "Independently of mTOR, Beclin1 was found to be closely associated with the regulation of SPINK1-stimulated autophagy, which more likely shed light on the discovery of a new pathway responsible for SPINK1’s function in colorectal and other types of cancers." (PMID 37305325, 2022). "The PI3K/AKT/mTOR signaling pathway is crucial for various cellular processes, including cell growth and division, metabolism, and migration, all of which can be dysregulated in cancer." (PMID 35887235, 2022). "The increased BCAA catabolism could contribute to enhanced energy generation and biomass production as well as promotion of mTOR signaling, which is a known cancer cell molecular pathway." (PMID 34921655, 2022). "Therefore, regulating the mTOR signaling pathway can result in cancer cell death with elevated autophagy, thereby highlighting its potential in the development of new cancer treatments." (PMID 35831271, 2022). "In the same context, PI3K/Akt/mTOR pathway is frequently deregulated in cancer cells." (PMID 36460880, 2022). "Targeting of the arginine pathway may be undertaken through use of ADI-PEG 20, which can chelate extracellular arginine and is being used in clinical trials for other cancers, and possibly in combination with mTOR-targeted approaches." (PMID 35326708, 2022). "iii.mTORC1 inhibits autophagy, and treatment with an mTOR inhibitor may induce autophagy, thus promoting cancer cell survival, as seen with AZD8055." (PMID 36109789, 2022). "Whether and how RalA is involved in mTOR regulation of senescent-like cancer cell remains to be studied." (PMID 36267578, 2022). "It has been further demonstrated that there is a positive feedback loop between mTOR activation and the binding of CXCL12 to its receptor CXCR4—inhibiting the mTOR activity may prevent cancer metastasis because it subsequently decreases CXCL12 interaction." (PMID 36168036, 2022). "In addition, one study reported that curcumin reduced α-KG levels by inhibiting BCAT1 expression and the mTOR pathway, and finally induced apoptosis in cytarabine-resistant ML cancer cells." (PMID 36119495, 2022). "The administration of BEZ235 to improve glucocorticoid resistance in pediatric T-ALL and the use of PKI-587 to decrease cancer cell proliferation in T-ALL demonstrated that dual PI3K/mTOR inhibitors significantly improved the treatment effect compared with inhibiting mTOR or PI3K alone." (PMID 36539659, 2022). "Moreover, increased eukaryotic translation initiation factor (eIF4E) overexpression renders cancer cells resistant to mTOR inhibitors." (PMID 35831271, 2022). "The mTOR pathway has also been shown to regulate cancer metabolism." (PMID 35327484, 2022). "Thus, the mTOR-eIF4E pathway represents important therapeutic targets for cancer with aberrant Akt activation." (PMID 36180910, 2022). "As a result, targeting this pathway for cancer treatment impacts key cellular processes in unpredictable ways, which might lead to mTOR inhibition resistance or perhaps a worsening of tumor development." (PMID 36109789, 2022).
cancer (continued). "Its anticervical cancer activity was associated with RTK downregulation and Akt-mTOR inactivation." (PMID 39282148, 2022). "Previous studies confirmed that Postn is closely related to cancer progression and may promote tumor invasion through the ILK (Integrin-linked protein kinase)/RAC-alpha serine (AKT)/Serine/threonine-protein kinase mTOR (mTOR) pathway." (PMID 35676936, 2022). "The increase in insulin sensitivity caused by metformin inhibits cancer cell growth by activating AMP kinase (AMPK), which then inhibits the PI3K/Akt/mTOR signaling pathway through mTOR phosphorylation resulting in rapid inhibition of protein synthesis and cell growth." (PMID 35800881, 2022). "In an effort to investigate the hypothesis that the Akt/mTOR pathway is a major molecular cascade triggered in a wide range of cancers, and its activation can lead to cancer progression." (PMID 36290632, 2022). "The mammalian target of rapamycin (mTOR) was reported as the main target of PA in cancer cells." (PMID 35250970, 2022). "The most prevalent alterations of MTOR in malignant tumors are E1799K, S2215F, and amplification." (PMID 35402264, 2022). "In addition, plenty of preclinical studies support that mTOR is an important therapeutic target in cancer." (PMID 35372044, 2022). "Over the last decade, mTOR inhibitors, including the natural compound rapamycin and its synthetic analogs (e.g. temsirolimus, everolimus, ridaforolimus), have been developed for cancer therapy and immune modulation." (PMID 35013125, 2022). "Interestingly, the mTOR signaling pathway is one of the most important signaling pathways during EMT process in multiple cancers, including HCC." (PMID 35433409, 2022). "An analysis based on KEGG found that the over-expressed genes were mainly concerned with ferroptosis, cancer-related microRNAs expressing, central carbon metabolism in cancer cells, mTOR signaling pathway, hypoxia-inducible factor (HIF)-1 signaling pathway, and the VEGF signaling pathway." (PMID 35550563, 2022). "CYFIP1 overexpression may play an important role in cancers with a predominantly altered mTOR signaling pathway." (PMID 36226166, 2022). "Cancer growth in bone requires the activation of various signaling pathways in cancer cells and stromal cells, including those stimulated by TGF-β and RANKL and mediated through Src tyrosine kinase, mTOR signaling mediated by mutations in TSC2 and the Wnt/β-catenin pathway." (PMID 36005209, 2022). "Similarly, it was found that the IL-22 secreted by cancer-related fibroblasts elicits a protumor effect on NSCLC cell lines through the PI3K-Akt-mTOR signal pathway." (PMID 35669104, 2022). "Moreover, pathway analyses showed that the DEGs were involved in multiple cancer-associated pathways, such as TGF-β, mTOR, IGF-1, NF-κB and PTEN pathways in LUAD." (PMID 36446361, 2022). "The mTOR signaling pathway plays an important role in maintaining cell growth, proliferation, motility and survival and is involved in the development of a variety of cancers." (PMID 36005209, 2022). "Interestingly, PI3K/Akt/mTOR signaling pathway is also often dysregulated in many cancer pathologies." (PMID 35244142, 2022). "Insulin, IGF-1 and IGF-2 could activate the PI3K/Akt/mammalian target of rapamycin (mTOR) signaling pathway, thereby promoting the development of cancers." (PMID 35222270, 2022).
cancer (continued). "Notably, previous studies have broadly suggested that increased PI3K/AKT/mTOR signaling is associated with sensitivity to PI3K inhibitors in LNCaP cell lines and other PTEN null cancer cell lines." (PMID 36167836, 2022). "Mechanically, sophocarpine exerted its anti-cancer effects by inactivating PI3K/AKT/mTOR signaling." (PMID 36132221, 2022). "Overall, the development of representative experimental models (PDXs and PDX-derived cell lines) has helped to identify the unique sensitivity of the CDS to AKT/mTOR inhibitors and trabectedin, revealing a mechanism-based therapeutic strategy to fight this lethal cancer." (PMID 34903601, 2022). "Indeed, mTOR inhibitors are a novel family of medications that are commonly employed in cancers, microbial infections, and immunosuppressive treatments." (PMID 36293326, 2022). "The PI3K/Akt/mTOR pathway is usually activated in cancer, and inhibition may have an anti-cancer effect." (PMID 35799780, 2022). "This alludes to a model whereby activation of IGF1R/AKT axis promotes survival of cancer cells with complex IV dysfunction by driving glycolysis, while concomitant suppression of mTOR is required to decrease energy consumption and thus compensate for disrupted mitochondrial ATP production." (PMID 35302710, 2022). "With regard to immunosuppressant therapy at discharge, cancer groups used less T-cell-depleting antibodies (29.6%–31.4% vs. 28.3%) and mTOR inhibitors (5.2%–6.1% vs. 7.7%), but more tacrolimus (72.7%–74.9% vs. 71.8%) and mycophenolic acid (MPA; 84.3%–84.9% vs.81.9%)." (PMID 36505816, 2022). "A study thought that GALNT2 may promote cancer progression via activating EGFR/PI3K/Akt/mTOR pathway." (PMID 36060650, 2022). "A vital target for cancer therapy, mTOR activation occurs often in human tumours." (PMID 35614940, 2022). "Hyperactivation of the PI3K/AKT/mTOR pathway occurs in nearly all malignant neoplasms." (PMID 36539659, 2022). "The mTOR signaling pathway may be proposed as a cancer biomarker, and its targeting constitutes a major therapeutic challenge." (PMID 36428613, 2022). "A main reason for the modest efficacy of mTOR inhibitors may be the pleiotropic activity profile of mTOR characterized by interaction with multiple hallmarks of cancer, such as proliferation, tumor metabolism, and immune response, besides autophagy." (PMID 35814409, 2022). "In addition, Torin-1 is an inhibitor of mammalian target of rapamycin (mTOR), which has been considered an important regulator of cancer." (PMID 36286020, 2022). "It has been reported that m1A modulates the PI3K/AKT/mTOR pathway in gastrointestinal cancers, and the dysregulation of this pathway has been identified as a key factor contributing to poor survival in several cancers." (PMID 35240991, 2022). "The mechanistic Target of Rapamycin (mTOR) integrates growth factor signaling and nutrient levels with growth and survival and plays an essential role in the proliferation and metabolism of cancer cells." (PMID 35963851, 2022). "In addition, rapamycin can inhibit PD-L1 expression in cancer cells, such as gastric cancer and lung cancer, by inhibiting mTOR and activating autophagy." (PMID 36077620, 2022). "The mTOR pathway is widely deemed as an appealing cancer therapeutic target." (PMID 36396656, 2022). "Furthermore, elimination of S6K1 activation by mTOR inhibition enhanced the anti-cancer effect of canonical HH pathway inhibition." (PMID 35406578, 2022). "The protein kinase B (AKT)/mammalian target of rapamycin (mTOR) signaling pathway plays an essential role in enhancing the invasiveness of cells, and inhibition of this pathway can effectively reduce the invasiveness of various cancer cells." (PMID 36339404, 2022). "Overall, mTOR pathway inhibitors alone are primarily cytostatic, thus they are more synergistic in combination with other targeted chemotherapeutic approaches to induce apoptosis of these cancer cells." (PMID 36146655, 2022).